SLC6A14 (solute carrier family 6 member 14)
Diseases named in the same sentence as SLC6A14 in open-access papers (continued):
Sharing a sentence is not in itself a finding about the gene and the disease.
tumor (continued). "Anticancer strategies (transporter inhibitors to starve tumor cells of essential amino acids or cytotoxic molecules that could be selectively transported by SLC6A14) are also being actively explored for other tumor types which have been shown to overexpress SLC6A14." (PMID 26106611, 2015). "In colorectal cancer, SLC6A14 enhances serine synthesis via JAK2/STAT3 signaling, while its inhibition suppresses Wnt/β-catenin signaling and reduces tumor growth." (PMID 41444422, 2025). "SLC6A14 and high CXCL5 demonstrated elevated expression in tumor cells compared to normal epithelial cells." (PMID 39670859, 2025). "Tumor–immune system interactions and drug bank (TISIDB) analysis confirmed a positive correlation between SLC6A14 and CXCL842." (PMID 41444422, 2025). "SLC6A14 and CXCL5 demonstrated the co-location with panCK, indicating them as specific tumor markers." (PMID 39670859, 2025). "This study identifies CXCL5 and SLC6A14 as key biomarkers of MVI, highlighting their roles in tumor proliferation, immune resistance, and poor clinical outcomes." (PMID 39670859, 2025). "Remarkably, we observed that SLC6A14 and CXCL5 were located in the same area within the ICC tumor cells, which aligns with the results obtained from the transcriptomics analysis." (PMID 39670859, 2025). "To validate SLC6A14 and CXCL5 at the protein level, we performed multiplex immunofluorescence on 20 patients with ICC, using panCK to annotate tumor cells." (PMID 39670859, 2025). "CXCL5 and SLC6A14 were identified as potential MVI biomarkers and showed high expression in tumor-invasive areas." (PMID 39670859, 2025). "We found that the expression of LAMC2, SLC6A14 and CTSE was distinctly increased in PC specimens and exhibited a dysregulated level in many types of tumors, suggesting their important function in tumor progression." (PMID 38267509, 2024). "After tumor formation, we treated mice with DOX to induce deletion of SLC6A14/12A4 or SLC6A14/25A15." (PMID 38066114, 2023). "Mechanistically, blockade of SLC6A14-mediated amino acid transport with α-MLT leads to amino acid deprivation, eventually inhibiting mTORC1 signaling pathway, in tumor cells." (PMID 35212370, 2022). "Further knockdown SLC6A14 with siRNA or treatment with α-MT in CRC cell lines reduced cell proliferation and migration in vitro and inhibited xenograft tumor growth in vivo." (PMID 35907820, 2022). "Deletion of Slc6a14 in this mouse attenuates PDAC growth, decreases the metastatic spread of the tumor, reduces ascites fluid accumulation, and improves overall survival." (PMID 35212370, 2022). "The transporter SLC6A14, which transports 18 of the 20 amino acids including all EAAs, was found to be upregulated in PDAC PDXs, primary tumour tissues and cell lines compared to normal tissue or cells, but not in GBM and HCC." (PMID 34588983, 2021). "The expression and leucine transport of SLC6A14 are regulated by PKC, which is a downstream molecule of mTORC2 and an important signal molecule regulating tumor cell proliferation." (PMID 34095122, 2021). "We propose that the combined targeting of SLC6A14 and AMPK can be exploited as a therapeutic approach to starve tumor cells." (PMID 33400734, 2020). "Supporting these notions, we show here that under methionine starvation coupled to SLC6A14 deletion, AMPK activation supports cell viability, thus, its genetic inhibition upon stress induces tumor cell death." (PMID 33400734, 2020). "Our study identifies SLC6A14 as a pivotal regulator of gemcitabine resistance and immune evasion in PDAC through its effects on glutamine metabolism, immune checkpoint signaling and tumor–stroma interactions." (PMID 41444422, 2025).
tumor (continued). "This study further suggests that the first FDA‐approved SLC6A14 inhibitor is worthy of development as a new therapeutic strategy for patients with EOBC, who often face significant challenges due to chemoresistance and aggressive tumor behavior." (PMID 40959920, 2025). "The absence of SLC6A14 within patient tumors was associated with shorter patient survival rates, suggesting that SLC6A14 is expressed specifically in less aggressive HCC tumor subtypes." (PMID 39062801, 2024). "Interestingly, SLC6A14, SLC34A2, and SLC5A1 also resulted among the top DEGs SLC when comparing each TCGA tumor type with matched normal tissue." (PMID 37397501, 2023). "The Erlotinib showed only one negative correlation with the SLC6A14 gene that was upregulated in 15 tumor types including PRAD compared to pooled GTEx control group, as well as in tumors with C2-C3 signature." (PMID 37397501, 2023). "α-MT can suppress colony-forming ability and cell cycle arrest in SLC6A14-positive tumor cells, whereas SLC6A14-negative cell lines are not affected." (PMID 35907820, 2022). "SLC6A14 was upregulated in CRC and could promote tumor progression by activating the Akt-mTOR signaling pathway, which may serve as an effective molecular target for the treatment of CRC." (PMID 35907820, 2022). "Subsequently, we provided evidence that knockdown of SLC6A14 expression or treatment with α-MT reduced CRC cell proliferation and migration in vitro through restricting amino acids uptake and inhibited xenograft tumor growth in vivo." (PMID 35907820, 2022). "Interestingly, SLC6A14 inhibition with α-methyltryptophan induced amino acid starvation in PDAC cells and not only reduced tumour growth and proliferation in vivo and in vitro, but also CSC-related features such as clonogenicity and invasiveness." (PMID 34588983, 2021). "Both facts might explain the observation that qPCR results only revealed trends, not significant changes, in the expression levels of DUSP1, CYR61, SLC6A14 and DUOX2 in tumor ischemic colorectal tissue samples." (PMID 26222051, 2015). "SLC6A14 inhibition noticeably reduced tumor growth and weight without affecting body weight." (PMID 41444422, 2025). "Notably, among the top-ranked CTD-suppressed genes, we found that five genes, including TOP2A, ACSL4, SQLE, CDK4, and SLC6A14 were significantly elevated in HCC clinical specimens, suggesting that NCTD targets to inhibit the expression of these genes to exert anti-tumor effects in HCC." (PMID 40271060, 2025). "Furthermore, SLC6A14 expression was higher in tumors occurring at a younger age and positively correlated with the expression of CD133 and the rate of tumor growth in HER2‐Tg mice." (PMID 40959920, 2025). "Moreover, SLC6A14 was among the top two upregulated SLC genes in 6 tumor types (PAAD, COAD, READ, STAD, ESCA, and CESC), while it was downregulated in MESO when performed differential analysis between each tumor type and matched normal tissue." (PMID 37397501, 2023). "The presence or absence of SLC6A14 expression varied significantly among different tumor types." (PMID 36371738, 2023). "Alpha-methyltryptophan (α-MT), an inhibitor of this transporter, induces amino acid starvation and autophagy in tumor cells by blocking SLC6A14, inhibiting mTOR signal transduction, inducing amino acid starvation, and inhibiting tumor cell growth and proliferation." (PMID 37924140, 2023). "In cervical cancer, SLC6A14 expression was upregulated up to 5.6-fold accompanied by elevated inducible nitric oxide synthase (iNOS) levels, suggesting that enhanced arginine transport by ATB0,+ may contribute to increased nitric oxide production in the tumour microenvironment." (PMID 41302469, 2025). "However, under which conditions blocking SLC6A14 may lead to selective killing of tumor cells has not yet been explored." (PMID 33400734, 2020).
tumor (continued). "Furthermore, qPCR results confirmed the microarray expression data of RGS1 and EEF1A1 in tumor ischemic colorectal tissue samples whereas differential expression of DUSP1, CYR61, SLC6A14 and DUOX2 in tumor ischemic colorectal tissue samples could not be validated." (PMID 26222051, 2015). "This “non-basal-like non-classical” tumor subset expresses core signatures such as high TMPRSS4, SLC6A14, IFI27, CST1, and STYK1." (PMID 39774001, 2025).
intestinal disease (2 papers, 2021 to 2022). "Recently, some studies have explored the role of SLC6A14 in CF pathophysiology and begun to explain the reasons for its identification as a modifier gene of CF lung and intestinal diseases." (PMID 35372502, 2022).
metabolic disease (2 papers, 2010 to 2021). A congenital disorder (due to inherited enzyme abnormality) or acquired (due to failure of a metabolically important organ) disorder resulting from an abnormal metabolic process. "In addition, the SLC6A14 amino acid/acyl-carnitine transporter, which primarily carries large hydrophobic and cationic amino acids, was both identified in our analysis as relevant to OGTT and previously been found to be associated with metabolic disease." (PMID 20195502, 2010).
gastrointestinal tumors (1 paper, 2023). "Of note, SLC6A14 was strongly upregulated (log2FC ≥ 6) in 4 gastrointestinal tumors, including COAD, PAAD, READ, and STAD." (PMID 37397501, 2023).
SLC6A14 also shares sentences with these, for which no sentence is quoted: inflammatory bowel disease (3 papers); triple-negative breast carcinoma (3); colon adenocarcinoma (2); Diabetes (2); glioma (2); infection (2); pancreatic ductal adenocarcinoma (2); type 2 diabetes (2); allergic rhinitis (1); Crohn disease (1); cystinuria (1); emphysema (1); endometrial cancer (1); fatty liver (1); head and neck squamous cell carcinoma (1); Insulin resistance (1); intrahepatic cholangiocarcinoma (1); irritable bowel syndrome (1); ischemic colitis (1); leukemia (1); melanoma (1); osteogenesis imperfecta (1); pancreatic adenocarcinoma (1); pouchitis (1); skin carcinoma (1); spinal muscular atrophy (1).